EGF (epidermal growth factor)
Diseases named in the same sentence as EGF in open-access papers (continued):
Sharing a sentence is not in itself a finding about the gene and the disease.
breast carcinoma (continued). "In the literature, FB were also reported to induce EMT in breast cancer cells by the secretion of activating growth factors like TGF-β1, EGF, PDGF, HGF, and MMP." (PMID 37781195, 2023). "In breast cancer, ERK5 contributes to the response to EGF stimulation and is involved in the resistance to ErbB-2 (HER2) inhibitors by facilitating G1-S transition." (PMID 37420093, 2023). "Neurensin‐2 (NRSN2) also promotes breast cancer metastasis by activating the PI3K/AKT/mTOR and NF‐κB signaling pathways, and melittin suppresses EGF‐induced cell motility and invasion by inhibiting the PI3K/Akt/mTOR signaling pathway in breast cancer cells." (PMID 37249285, 2023). "EGF has been identified to induce both normal and malignant epithelial cell motility and to regulate EMT and has been connected to basal breast cancer progression." (PMID 37670250, 2023). "Melittin, the main peptide component of Apis mellifera venom, inhibits EGF-induced cell movement and invasion by inhibiting the PI3K/Akt/mTOR signalling pathway in breast cancer cells." (PMID 37033662, 2023). "The bioinformatic analyses demonstrated the positive association between the real metastatic microtumor environment and MCSs with respect to the cytoskeleton, the extracellular matrix, focal adhesion and EGF/MAP signaling, dependent on the breast cancer type." (PMID 36674696, 2023). "Among HIF1α responsive genes, there are several members involved in tumor growth, angiogenesis, and survival, and it has been demonstrated that in breast cancer cells, HIF1α directly regulates SCF gene expression also as a response to EGF." (PMID 37686233, 2023). "While the MDA-MB-231 cell line provides a model for more aggressive, hormone-independent breast cancer, the MCF-7 cell line has functional estrogen and EGF receptors, is dependent on estrogen and EGF for proliferation, and is noninvasive." (PMID 37571024, 2023). "BM in HER2-positive breast cancer was shown to be mediated by several ligands such as heregulin (HRG) and EGF." (PMID 37190188, 2023). "Trastuzumab is a monoclonal antibody used in the treatment of breast cancer in cases where the tumor overexpresses the HER2 receptor, a cell membrane receptor activated by the epidermal growth factor." (PMID 36009592, 2022). "TRPM7 channel expression can regulate epidermal growth factor (EGF)-induced signal transducer and activator of transcription 3 (STAT3) phosphorylation and expression of the EMT marker vimentin in human breast cancer cells." (PMID 35359592, 2022). "The ectopic expression of Sef suppresses breast carcinoma cell proliferation, whereas the inhibition of endogenous Sef expression promotes FGF- and EGF-dependent proliferation of cervical carcinoma cells." (PMID 35805075, 2022). "Finally, in the two cell lines that displayed aerotaxis independently of EGFR activation but stimulated by EGF, one was Basal A and the other was Basal B. Based on this analysis, the molecular subtypes of breast cancer cell lines do not seem to be linked to their aerotactic profiles." (PMID 36380366, 2022). "Three other breast cancer cell lines, namely MDA-MB-231, MDA-MB-157 and T47D, underwent aerotaxis independently of EGF and EGFR." (PMID 36380366, 2022). "To determine the impact of soluble factors on breast cancer cell motility, we added either CXCL12 or epidermal growth factor (EGF), or a combination of both, to our cell cultures just prior to time-lapse video recording." (PMID 35158871, 2022). "We have summarized how steroid hormones (E2 and PR) and growth factors (EGF/ERBB1 and HER2) can induce the transcription of PRLR, thereby increasing its expression in breast cancer cells and promoting cell proliferation." (PMID 36187116, 2022). "In another study, let-7a was encapsulated in epidermal growth factor (EGF), peptide-conjugated exosomes to target EGFR-expressing breast cancer cells." (PMID 35562884, 2022).
breast carcinoma (continued). "GFs regulating EGF and FGF signaling play major roles in the mammary epithelium during embryogenesis, post-natal development and has immense implications in breast cancer progression." (PMID 35504930, 2022). "In addition, EGF could stabilize PD-L1 via GSK3β inactivation in basal-like breast cancer." (PMID 35280982, 2022). "For example, the mRNA signatures ETFDH, EGF, PRKAB1, ALOX5, DHRS9, MTHFR, and MGHH are in the maximum interaction network and are connected to other breast-cancer-related, frequently altered genes." (PMID 36551179, 2022). "In breast cancer, HMGA1, EGF and TGFβ signaling pathways, HIF-1α all promoted EMT by upregulating FOXM1." (PMID 35197112, 2022). "In breast cancer cells, HIF-1α is required for upregulation and secretion of the pro-tumorigenic cytokine Stem Cell Factor (SCF) by EGF." (PMID 35158804, 2022). "In glioblastomas, EGF signals through c-SRC/PKC-δ/sphingosine kinase-1, whereas in breast cancer and OVCA EGF signaling is mediated via NF-κB and ELK1." (PMID 35267539, 2022). "In breast cancer, it was determined that hsa-miR-200bc/429 cluster directly targets PLCG1 and regulates EGF-driven invasion." (PMID 37533517, 2022). "In breast cancer, FGF2 is also positively correlated with epidermal growth factor (EGF) and insulin-like growth factor (IGF)." (PMID 36111743, 2022). "In one study using normal human epidermal keratinocytes, 2 nM EREG induced ERK phosphorylation more strongly than 10 nM EGF, whereas in another study using MCF-7 mammary cancer cells, 10 μM EREG and 16 nM EGF induced ERK phosphorylation to a similar level." (PMID 34667080, 2022). "The expression level of miR-23b is induced by the HER2/neu, EGF, TNF-α, and Blimp1, constitutively activated in breast cancer." (PMID 34777498, 2021). "In the present study, we showed that the PLD inhibitor FIPI potently blocked EGF-induced calcium release and EGF-induced migration in MDA-NEO and MDA-HER2 breast cancer cells." (PMID 33832505, 2021). "In contrast to ERK1/2, EGF-mediated activation of ERK5 occurs independently of RAS and requires MEK5 in breast cancer cells." (PMID 34572912, 2021). "In the present study, we investigated the role of PLD in the EGF-induced migration of MDA-NEO and MDA-HER2 breast cancer cells." (PMID 33832505, 2021). "PRL and EGF via their cognate receptors synergistically induce MEK/ERK1/2 and PI3K/AKT pathways which promote proliferation, survival, and invasion of breast cancer cells." (PMID 34572912, 2021). "One such example involves EGF/CSF1 paracrine loop between breast cancer cells and macrophages, where tumor cells secrete CSF1 to recruit macrophages, and in turn, macrophages release EGF to stimulate tumor cell invasion towards blood vessels." (PMID 33540535, 2021). "In summary, FIPI potently blocked EGF-induced calcium release in MDA-NEO and MDA-HER2 human breast cancer cells." (PMID 33832505, 2021). "FGF2 has been associated with the regulation of tumour angiogenesis and metastasis, and has been positively correlated with epidermal growth factor (EGF) and IGF in breast cancer." (PMID 33573134, 2021). "Both the spontaneous and 100 ng/ml EGF-induced migration of MDA-NEO and MDA-HER2 human breast cancer cells was significantly blocked by 100 nM FIPI." (PMID 33832505, 2021). "P2RY13 is a G-protein-coupled receptor, and it was reported to be decreased upon epidermal growth factor (EGF)- and hypoxia-induced epithelial–mesenchymal transition (EMT) in breast cancer cells." (PMID 35140706, 2021).
breast carcinoma (continued). "The choice of treatment for breast cancer (BC) depends on the expression level of the estrogen and progesterone receptors (ER and PR), HER2 (a receptor for epidermal growth factor), and Ki-67." (PMID 35055320, 2021). "Second, in breast cancer cells, GPER integrates assembly of the fibronectin matrix with the release of EGF; thus satisfying two basic requirements or cellular survival: attachment to the extracellular matrix and responsiveness to growth factors." (PMID 33329395, 2020). "On the other hand, previous studies have indicated that over-expression of miR-21 leads to amplified invasion of MCF-7 cancer cells, and enhanced EGF-mediated invasion and TGF-β-mediated invasion in breast cancer." (PMID 33061847, 2020). "There is evidence showing that STAT3 activation is dependent on Ca2+ signal in breast cancer cells, and phosphorylation of STAT3 at Tyr705 by EGF can be substantially inhibited upon intracellular Ca2+ chelation." (PMID 32517717, 2020). "We used mass cytometry to measure EGF signaling dynamics in the ERK and AKT signaling pathways before and after induction of EMT in Py2T murine breast cancer cells." (PMID 33329028, 2020). "Epidermal growth factor (EGF) signals have been confirmed to be overexpressed and are involved in the development of breast cancer." (PMID 32792949, 2020). "Epidermal growth factor (EGF) promotes ANO1 expression in colonic epithelial cancer cells and in breast cancer cells." (PMID 33250781, 2020). "ERRα up-regulates not only the recruitment to breast cancer biomarker gene TFF1 promoter, but also its expression upon breast cancer cell treatment with epidermal growth factor (EGF)." (PMID 31894856, 2020). "Suppression of increases in cytosolic free Ca2+ ([Ca2+]CYT) reduces the induction of EMT genes normally induced by epidermal growth factor (EGF) and hypoxia in MDA-MB-468 breast cancer cells." (PMID 33322037, 2020). "Following identification and verification of Annexin A2 as a protein newly synthesized in EGF mediated MDA-MB-231 cell migration and invasion, we next examined its expression profile across a number of breast cancer cell lines." (PMID 32629869, 2020). "Levels of vascular endothelial growth factor (VEGF), epidermal growth factor (EGF) and carcinoembryonic antigen (CEA), for example, have been described to be significantly elevated in breast cancer patients." (PMID 33293589, 2020). "Work done predominantly in colon and breast cancer shows that the latter is mainly a consequence of the antagonism that these molecules exert on Wnt/β-catenin, TGF-β and EGF signaling pathways." (PMID 32854355, 2020). "Further investigation with the inhibitor showed that preventing Rac1 activation by ZINC69391 reduced EGF-induced actin reorganization and reduced cell migration as assayed by wound healing in MDA-MB-231 and F3II breast cancer cells." (PMID 32992837, 2020). "We also compared the concentrations of EGF, TGF-β, and bFGF between the ACM and FBS media from solid tumor cultures of breast cancers (n = 6)." (PMID 33235257, 2020). "When cultured in serum-free medium, EGF significantly accelerated the synthesis rates of DAG, TAG, phosphatidylethanolamine (PE) and phosphatidylserine (PS) in these two breast cancer cell lines when normalised to protein abundance." (PMID 33203880, 2020). "In our previous study, we found that epidermal growth factor induced the expression of fascin-1 by activating p44/p42 MAPK (ERK1/2), which subsequently promoted breast cancer cell migration and invasion." (PMID 32420377, 2020). "In MCF-7 breast cancer cells, activation of the ErbB receptor by HRG and EGF elicits two different biological responses." (PMID 32605138, 2020).
breast carcinoma (continued). "Binding and internalisation of 111In-EGF-AuNPs by breast cancer cells was EGFR-dependent and was 12-fold higher for MDA-MB-468 than MCF-7 human breast cancer cells with high or low EGFR expression, respectively." (PMID 31659527, 2019). "This controversy has been also reported in breast cancer cells, in which the pre-treatment of MCF-7 cells with exogenous GM3 decreased the stimulatory effect of EGF on cell proliferation." (PMID 31578452, 2019). "Our previous work identified a novel link between MICAL1 and RAB upon EGF stimulation and found that MICAL1 was essential for maintaining invasive phenotype of breast cancer cells." (PMID 31019460, 2019). "In the current study, a new liposome, 111In-EGF-LP-Dox, was designed for chemo-radionuclide therapy of EGFR-positive cancer and the use of US-induced cavitation to enhance its delivery to breast cancer tumour models was investigated." (PMID 31534505, 2019). "Regarding the EGFR ligands, we found that EGF was the predominant EGFR ligand in lymphoma, hepatocarcinoma, colon carcinoma, melanoma, breast cancer, myeloma and reticulum cell sarcoma cell lines." (PMID 31921216, 2019). "EGR1 expression mediates an EGF-ERK signaling cascade was reported in prostate cancer cells and breast cancer cells, which contributes to the migration of cancer cells." (PMID 31501409, 2019). "In this study, we identified ADD1 as a novel substrate of Cdk5 and demonstrated that ADD1 phosphorylation at T724 by Cdk5 is important for EGF-induced cell migration and invasion in MDA-MB-231 breast cancer cells." (PMID 31548578, 2019). "We reported a novel EGF/EGFR axis that negatively fed back on the AJAP1-mediated β-catenin expression pathway and it accelerated breast cancer progression." (PMID 31171012, 2019). "In these two breast cancer cell lines, HER2 was bound to the chromatin in both vehicle and EGF stimulated conditions, confirming previous findings showing that full-length HER2 can be chromatin bound." (PMID 31747426, 2019). "Autocrine EGF signaling consistently induces VEGF-A expression and secretion by colon, gastric and breast cancer cells, leading to a paracrine VEGF-A-induced tumor angiogenesis that supports tumor growth and progression." (PMID 31717527, 2019). "For instance, survivin is regulated by several growth factors and their respective receptors, including epidermal growth factor (EGF) and fibroblast growth factor (FGF) in breast cancer cells." (PMID 31817839, 2019). "Altogether, our findings reveal an EGF signaling cascade involving EGFR, c-Src, and HDAC3 in breast cancer cells." (PMID 31430896, 2019). "In an EGF-induced EMT model, MYOF ablation impairs the ability of breast cancer cells to undergo EMT." (PMID 30213946, 2018). "It has been reported that Pyk2 is a key effector of EGFR and HER2 signaling in breast cancer, in which Pyk2 is activated by EGF and heregulin (HRG), and positively regulates EGF/HRG-induced cell migration and invasion." (PMID 29738483, 2018). "For example, melittin, the major peptide component in the venom of honey bee Apis mellifera, has been shown to suppress EGF-induced cell motility and invasion by inhibiting PI3K/Akt/mTOR signaling pathway in breast cancer cells." (PMID 30400202, 2018). "To extend our findings to other breast cancer models of EGFR signaling, we applied a similar EGF–trametinib treatment combination to our dox-inducible model of EGFR expression in the metastatic Ca1a cells." (PMID 30250119, 2018). "This study identified an oncogenic role for HIST2H2AC, as a regulator of EGF/FGF2 signaling and breast cancer pathophysiology." (PMID 30165676, 2018). "The regulation of the expression of EGF and its downstream genes in the MAPK pathway, such as RRAS and MAPK3, have also been described as important inhibitors of apoptosis on breast cancer cells induced by chemotherapeutic agents." (PMID 30173296, 2018).
breast carcinoma (continued). "In human breast cancer, phosphorylation of WBP2 at Tyr192 and Tyr231 was regulated by c-Src and c-Yes kinases and was stimulated by EGF." (PMID 30001383, 2018). "Inhibition of EGF-mediated ERK activation by full-length EpCAM has been reported in carcinoma cells, including breast cancer lines." (PMID 30261040, 2018). "In the PyMT model of breast cancer, we have shown that myoepithelial cells and growth factors AREG, EGF, and bFGF suppress PyMT expression." (PMID 30367629, 2018). "Macrophages, for example, when exposed to type 2 cytokines like IL-4, express epidermal growth factor (EGF) and vascular endothelial growth factor (VEGF), and enhance angiogenesis and mammary carcinoma metastasis." (PMID 29751789, 2018). "In breast cancer cells, translocation of EGFR to mitochondria has been shown to occur upon EGF stimulation resulting in phosphorylation of the cytochrome c oxidase subunit II." (PMID 29124875, 2018). "In rat PC12 cells and in human breast cancer MCF7 cells, sustained ERK activity results in cellular differentiation, whereas transient activity elicited by epidermal growth factor (EGF) results in proliferation." (PMID 28468958, 2017). "EGF activated STAT3 via gp130-independent EGFR and a strong correlation was found between nuclear STAT3 activation and EGFR expression in breast cancers through immunohistochemical analysis." (PMID 27861147, 2017). "This study investigated the effect of N-linked glycosylation on the binding of Herceptin to HER2 protein in breast cancer and on the sensitivity of cancer cells to the chemotherapeutic agent doxorubicin (DXR) and growth factors (EGF and IGF-1)." (PMID 28223691, 2017). "Primary and secondary mammosphere assays were performed to implicate phospho-Ser294 PRs, epidermal growth factor signaling, and RUNX2 in breast cancer stem cell biology." (PMID 28412963, 2017). "The EGF–RAS–RAF–MEK–ERK pathway is frequently activated in various cancers, including breast cancer, and plays a critical role in tumor growth." (PMID 29212253, 2017). "Epidermal growth factor (EGF) binds EGFR, while heregulin (HRG) binds HER3 and HER4, and all three receptors dimerize with HER2 as the preferred co-receptor in HER2+ breast cancer cells, thus increasing HER2 activity." (PMID 29088778, 2017). "Treatment with Iressa eliminates the increase of phosphorylated WBP2 induced by EGF in breast cancer cells, indicating that phosphorylation of WBP2 is an indispensable component of EGF signaling and the gefitinib pharmacogenomic pathway in breast cancer." (PMID 28724435, 2017). "We have shown in different breast cancer cell lines (such as SKBR3, MDA-MB468, and BT20) that EGF is sufficient to call up tTG expression and activation." (PMID 28423611, 2017). "For instance, TGF-β1 induces EMT by the transactivation of EGFR/EGF signaling through HA/CD44 in lung and breast cancer cells." (PMID 29261154, 2017). "BMP-4 is considered as an inhibitor of breast cancer cell growth, but can also have a synergistic effect on proliferation of breast cancer cells induced by fibroblast growth factor (FGF), EGF and HGF." (PMID 28733469, 2017). "Our studies showed that CNR2 activation inhibited EGF and IGF-I-induced migration and invasion of ERα+ and ERα- breast cancer cells." (PMID 27213582, 2017). "We and others have also previously reported that both EGF and MAPK enhanced breast cancer cell migration and invasion." (PMID 29142206, 2017). "We show here that both the MUC1 extracellular and intracellular domains contribute to EGF-induced EGFR activation in human colon and breast cancer cells with the predominate contribution from the MUC1 extracellular domain." (PMID 28731466, 2017). "In conclusion, the AKT-mTOR-STAT3 signaling axis contributes to EGF-induced CCR1 expression, which promotes invasion and metastasis in breast cancer cells." (PMID 29212252, 2017).